CRP (C-reactive protein)
Diseases named in the same sentence as CRP in open-access papers (continued):
Sharing a sentence is not in itself a finding about the gene and the disease.
depression (continued). "Furthermore, in a meta-analysis of cross-sectional studies, adjustment for BMI led to a substantial attenuation of the effect sizes for the association between CRP and depression." (PMID 28128231, 2017). "Also in healthy individuals is depression (ZSDS) associated with inflammation marker C-reactive protein (CRP), leukocytes, and fibrinogen, as a regional Greek study found." (PMID 28012071, 2017). "Depression was associated with high levels of CRP and low levels of FeNO." (PMID 28403218, 2017). "Serum concentration of CRP is a complicated diagnostic biomarker of depression." (PMID 29217840, 2017). "Interestingly, higher levels of CRP and IL-6 during childhood (age of nine years) were shown to be a predictor of higher risk of depression and psychosis in later life." (PMID 29181395, 2017). "In conclusion, these results confirm and extend previous findings suggesting that increased levels of CRP are associated with a later onset of depression and demonstrate that also NLR as a subclinical inflammatory marker is related to a later onset of depression." (PMID 29218020, 2017). "In addition to these studies, the current GWAS data do not corroborate epidemiological observations suggesting that elevated CRP levels are associated with amyotrophic lateral sclerosis, Alzheimer disease, Parkinson disease, and major depressive disorder." (PMID 27327646, 2016). "Therefore, it is plausible that the associations of hopelessness with IL-6 and CRP and of depression with CRP and MMP-9, all of which vanished after adjustment for physical and lifestyle factors, are mainly reliant on lifestyle factors." (PMID 26979423, 2016). "Indeed, associations between depression and the level of biomarkers, such as C-reactive protein (CRP), haemoglobin (Hb), thyroid-stimulating hormone (TSH) and vitamin D, have been reported." (PMID 26788321, 2015). "Accumulating evidence suggests that depression might be associated with activated inflammatory processes: e.g., depressed patients with elevated c-reactive protein (CRP), acute phase proteins, and pro-inflammatory cytokines." (PMID 26615538, 2015). "The third National Health and Nutrition Examination Survey (NAHANS III) database revealed that the association between depression and elevated levels of CRP was apparent in young male adults, and the comparable association was quite weak and not significant in women." (PMID 27429271, 2014). "A second explanation is that viral infections affect cognitive functioning through systemic inflammation, demonstrated by associations with C-reactive protein (CRP) in elderly, in healthy adults, in patients with schizophrenia and in patients with major depression." (PMID 24983885, 2014). "Depression is associated with an innate inflammatory response, and a meta-analysis by Howren and colleagues has shown depressive symptoms to be positively associated with CRP, IL-1 and IL-6 in both clinical and community samples." (PMID 24239712, 2014). "Depression is also linked to an inflammation marker in blood called C-reactive protein (CRP)." (PMID 24774860, 2014). "However, little is known about the direction of the causal relationship between depression and CRP for predicting CABG recovery." (PMID 24239712, 2014). "The depressive patients have higher serum HsCRP level than the non- depressive patients, and thus CRP may be as a new risk factor of depression in the dialyzed population." (PMID 24774860, 2014). "Interestingly, the inflammatory marker C-reactive protein (CRP) had the most consistent impact explaining 14–53% of the associations of anxiety and depression severity with abdominal obesity and dyslipidemia." (PMID 24109426, 2013). "Finally, another recent and large epidemiological study of men and women aged 20–100 years observed that increasing CRP levels were associated with increasing risk for psychological distress and depression." (PMID 24109426, 2013).
depression (continued). "The aim of this study was to investigate the prevalence of somatic, particularly cardiovascular comorbidity, and MBS and its components in patients with recurrent major depression, as well as the prevalence of increased CRP as an additional comorbidity risk factor." (PMID 24170724, 2013). "Changes in Hamilton Depression Rating Scale scores were significantly associated with changes in IL-6 (P = 0.003) levels; changes in Young Mania Rating Scale scores were significantly associated with changes in CRP (P = 0.006) and TNF-α (P = 0.039) levels." (PMID 23826157, 2013). "Meta-analysis confirmed the association between IL-6, CRP and IL-1β levels and depression." (PMID 24244750, 2013). "In addition, in a longitudinal study CRP levels at baseline were statistically associated with depression scores." (PMID 24385966, 2013). "Further, the CRP gene has been found to modify the relationship between depressive symptoms and circulating CRP level suggesting the possibility of such CRP gene by depression interactions in relation to risk of the metabolic syndrome." (PMID 21296145, 2011). "However, the association between personality traits and CRP was found also in women denying ongoing depression, suggesting that these personality traits per se are related to low-grade inflammation, irrespectively of an ongoing depression." (PMID 18384670, 2008). "Previous studies have suggested that the apparent association between symptoms of depression and CRP may be partly due to a confounding variable, e.g. high BMI." (PMID 18384670, 2008). "Moreover, reduced systemic inflammation reflected by lower IL-6 and CRP levels may decrease neuroinflammation and improve mood regulation, as chronic inflammation is implicated in depression pathogenesis." (PMID 40927565, 2025). "Furthermore, recent studies have suggested that variants of the CRP gene may influence circulating CRP levels and appear to be independent susceptibility factors for late-life depression." (PMID 40955269, 2025). "In addition, while most studies were purely descriptive, a subset integrated biological markers into NA models, revealing significant associations among fatigue, depression, sleep disturbances, and inflammatory biomarkers such as IL-6, CRP, and tumor necrosis factor-α." (PMID 40633921, 2025). "However, a closer analysis of patients with depression could document that the proportion of depression cases associated with inflammation was higher and underestimated by the CRP cut-off." (PMID 40141399, 2025). "Patients with significant depression consistently show elevations in immune markers linked with chronic inflammation, such as tumor necrosis factor, interleukin (IL)-1 beta, and interleukin-6 (IL-6), as well as acute phase proteins like C-reactive protein (CRP)." (PMID 40787495, 2025). "Importantly, the DI-GM score, which specifically captures dietary components favoring gut microbial health, showed even stronger inverse associations with depression, anxiety, and inflammatory markers, including CRP, IL-6, and fecal calprotectin, compared to the MIND score." (PMID 40927565, 2025). "Causal evidence for CRP and other proinflammatory markers [i.e., Glycoprotein Acetyls (GlycA): a composite biomarker thought to provide a more stable marker of inflammation which reflects the glycosylation of multiple acute-phase proteins] on depression are mixed." (PMID 40348744, 2025). "Additionally, it is important to note that the ABCD cohort primarily consists of healthy adolescents without clinical depression, which may further attenuate associations between PGS_CRP and depression scores." (PMID 40630521, 2025). "Notably, CRP was associated with a greater likelihood of meeting criteria for a range of clinical outcomes, with a numerically greater likelihood consistently reported for depression as compared to anxiety at baseline and first follow-up assessment." (PMID 38699368, 2024).
depression (continued). "In addition, PRSs for CRP may contain gene variants that are protective against MDD, thus suggesting that genotype and circulating levels of CRP could be independently associated with depression." (PMID 39766785, 2024). "However, the association between peripheral CRP levels and depression remains controversial." (PMID 38596631, 2024). "Also, magnesium deficiency may increase inflammatory factors like C-reactive protein which helps the development of depression." (PMID 38429766, 2024). "Additionally, magnesium exhibits certain immunoregulatory effects, which potentially interact with depression, particularly as magnesium deficiency may be associated with elevated levels of inflammatory markers such as serum C-reactive protein." (PMID 39564360, 2024). "Furthermore, it suggests that adipose tissue promotes pro-inflammatory cytokine secretion and stimulates CRP synthesis, which may then activate brain inflammatory processes implicated in depression aetiology." (PMID 36462595, 2023). "MR analyses provided some evidence that serum CRP may modestly increase anxiety and depression symptoms and reduce life satisfaction, with ~2% higher scores per doubling in serum CRP, but only the association with life satisfaction reached conventional criteria for statistical significance." (PMID 37217205, 2023). "This indicates that CRP could also be a risk factor for depression." (PMID 36960961, 2023). "Another study concluded that abnormal CRP may be linked to the stenosis of some cerebral arteries, and also, elevated hsCRP can possibly predict post-stroke disability, apathy, delirium, fatigue, cognitive impairment, and depression." (PMID 37873776, 2023). "However, our results remain consistent with the possibility that inflammation may cause depression, considered as a unitary entity, via non-CRP mediated processes." (PMID 36057695, 2022). "A population-based study investigating the role of gender in the association between CRP levels and depressive severity, recruited 231 individuals (142 female and 89 men) with MDD from the Genome-Based Therapeutics Drugs Depression (GENDEP) study." (PMID 35163538, 2022). "Similarly, chronically elevated IL-10 and CRP levels could help identify mTBI patients at risk of developing depression and PTSD." (PMID 35053845, 2022). "While inflammation in childhood is a risk factor for depression, anxiety, and psychosis, our novel approach was to identify a persistent clinically relevant phenotype (anxiety) and demonstrate relevance for psychosis, with potentially CRP mediating these associations." (PMID 35151465, 2022). "Considering that depression is a common comorbidity of migraine and shares pathogenic mechanisms with migraine, geographic distribution may be an explanation for the difference in the association between CRP levels and migraine noted among studies." (PMID 36313504, 2022). "Moreover, hs-CRP levels seem to be an independent risk factor of depression and elevated hs-CRP levels could be a predictor of the onset of MDD." (PMID 35163538, 2022). "Consequently, our data suggest that little decrease in CRP levels after MI could put patients with lifetime depression at risk for recurrent MI." (PMID 35566447, 2022). "Indeed, immune dysfunction is implicated in the etiology of both schizophrenia and depression with cytokines such as interleukin (IL) 6 and C-reactive protein (CRP) detected at elevated levels, and causality suggested in Mendelian randomization studies of both disorders." (PMID 35717212, 2022). "Finally, we conducted a multivariable Mendelian randomization (MVMR) analysis to examine the associations between genetically-predicted smoking behavior and risk of depression after adjusting for genetically-predicted proxies of generalized inflammation (CRP) and IL-6 activity." (PMID 36057695, 2022).
depression (continued). "However, the multivariate analysis of patients with depression could document that the proportion of cases with depression associated with inflammation was higher and underestimated by the CRP cut-off." (PMID 35409300, 2022). "Blood C-reactive protein (CRP) levels have additionally been associated with symptom severity in women, and meta-analyses of placebo controlled randomized controlled trials (RCTs) with anti-inflammatory treatment have shown beneficial effects on depression and depressive symptoms." (PMID 35022028, 2022). "Secondly, not all included studies controlled for potential confounding variables in the association between depression and inflammation and, hence, this may limit the generalizability of the findings in those studies which report positive associations between CRP levels and depression." (PMID 35163538, 2022). "Thus, possible associations between depression subtypes and its pathogenic characteristics with controls may be drawn through plasma levels of C-reactive protein (CRP), IL-6, IL-10, and leukocyte subpopulation in blood composition." (PMID 36217471, 2022). "Moreover, a correlation between high CRP levels and threat-related amygdala activity (a neural biomarker of depression and anxiety risk) as assessed with functional MRI (fMRI) during an emotional face-matching task, specifically in male undergraduate students was reported." (PMID 35558424, 2022). "Evidence from Mendelian randomization (MR) studies, which use genetic variants regulating levels/activity of a biomarker as proxies to address the issue of confounding, suggest that IL-6 and CRP could be potentially causally related to depression and psychosis." (PMID 33684738, 2021). "Several details remain unclear regarding these overall associations between CM, CRP and depression." (PMID 34867491, 2021). "While CRP and IL-6 are commonly measured inflammatory markers, they have multiple pro- and anti-inflammatory roles such as those exerted through IL-6 classic and trans-signalling, which complicates inferences about specific immunological mechanisms conferring risk for depression." (PMID 34135474, 2021). "However, compared with normal people, obese people with good metabolism have only a slightly increased risk of depression, but when obese people are accompanied by metabolic disorders (e.g., hypertension, dyslipidemia, high C-reactive protein or insulin resistance), the risk of depression is higher." (PMID 34531719, 2021). "Additionally, high consumption of red and processed meats (containing large amounts of saturated fatty acid) was associated with higher levels of low-grade inflammation (C-reactive protein) and subsequent brain atrophy that are positively associated with depression." (PMID 34024764, 2021). "Furthermore, we have carried out MR analysis in the full sample, and in men and women separately, to test whether associations of CRP and IL-6 with depression and anxiety are consistent with potential causal roles for these biomarkers in these conditions." (PMID 34505025, 2021). "The results revealed that pre-pandemic CRP concentrations were positively associated with depressive symptoms in the early months of the COVID-19 pandemic in England, independently of pre-pandemic depression, sociodemographic factors, lifestyle and health-related factors." (PMID 34887380, 2021). "Thus, it remains unclear whether moderate increases in CRP levels can indicate with confidence a risk for inflammation-associated depression." (PMID 32873895, 2021). "In addition, large consumption of red meats and processed meats that contain lots of saturated fatty acids was associated with higher levels of low-grade inflammation (C-reactive protein) and subsequent brain atrophy, which are positively associated with depression." (PMID 32908917, 2020).
depression (continued). "We have examined whether longitudinal patterns of inflammation, based on three CRP measurements from childhood to early-adulthood, are associated with the risk of depression in early-adulthood in the Avon Longitudinal Study of Parents and Children, a prospective birth cohort." (PMID 31707310, 2020). "We found trend evidence for an interaction between CRP and BMI (adjusted OR for the interaction term = 1.56; 95 % C.I. 0.98–2.02) and between CRP and triglycerides (adjusted OR for the interaction term = 1.17; 95 % C.I. 0.99–1.38) on risk of current depression." (PMID 32339985, 2020). "We found the evidence for an association of current depression with raised CRP and raised triglycerides, which is consistent with our recent MR study reporting that triglycerides, as well as IL-6 and CRP, could be causally linked to depression." (PMID 32339985, 2020). "Self-reported napping assessed in over 5,000 older participants was also associated with higher CRP levels, particularly in older participants, but the relationship was attenuated after adjusting for health-related variables such as pre-existing diseases, blood pressure, and depression." (PMID 30920354, 2019). "Therefore, routine CRP screening in patients with depression, and identification and treatment of the cause of inflammation could improve overall health-related mortality and morbidity." (PMID 31258105, 2019). "Finally, CRP is only one of many markers of peripheral inflammation that have been or could be linked to depression." (PMID 29764522, 2019). "Population-based longitudinal studies show that higher levels of CRP and IL-6 at baseline are associated with an increased risk of depression in subsequent follow-ups, suggesting that inflammation could be a cause rather than simply a consequence of the illness." (PMID 31258105, 2019). "Population-based longitudinal studies have reported that higher levels of IL-6 and CRP are associated with symptoms/diagnosis of depression, mania and psychosis subsequently in life, suggesting low-grade inflammation could be a cause for these illnesses, rather than simply being a consequence." (PMID 29544672, 2018). "Moreover, Maes and fellow workers have established an association between the presence of functional SNPs in TNF-α, IL-1β and CRP and an increased risk of developing depression and, indeed, responsiveness or otherwise to the administration of antidepressant therapy." (PMID 29294244, 2018). "As a marker of inflammation measured in the periphery, high CRP may reflect activity of more upstream pro-inflammatory factors, such as IL-6 and IL-1B which may themselves induce changes in brain function predisposing to depression." (PMID 28809860, 2017). "Therefore, the reasoning that elevated inflammation might contribute to depression should be considered with caution despite findings reporting higher susceptibility to depressive symptoms in women with elevated CRP levels." (PMID 28848457, 2017). "One previous meta-analysis assessing the association between CRP, IL-6 and depression employed more relaxed inclusion criteria and sample material which may partially explain the smaller overall effect size estimates described in that study (CRP, d = 0.15 and IL-6, d = 0.25)." (PMID 26065825, 2015). "In addition to a neurotoxic effect of glucocorticoids, support for the physiologic stress of DKA and its treatment is also associated with a systemic increase of CRP thus supporting roles for both physiologic and psychological stress in the pathogenesis of cognition and depression." (PMID 26831554, 2015). "Several biological mechanisms including decreased heart rate variability, increased platelet aggregation, higher levels of inflammatory risk markers (C-reactive protein and interleukin-6) among individuals with depression and/or anxiety may lead to increased risk for cardiovascular diseases." (PMID 24433257, 2014). "Moreover, raised CRP and IL-6 predicted subsequent risk of depression." (PMID 24481186, 2013).